BRCA1 (BRCA1 DNA repair associated)
Diseases named in the same sentence as BRCA1 in open-access papers (continued):
Sharing a sentence is not in itself a finding about the gene and the disease.
breast cancer (continued). "BRCA1/2 are important genes that affect HR ability, and BRCA1/2 mutations have been used to predict platinum sensitivity in ovarian and breast cancers." (PMID 36591485, 2022). "In an accompanying in vivo experiment, EZH2 inhibition was shown to improve the antitumor effect of platinum drugs in BRCA1-deficient murine mammary tumors." (PMID 36230683, 2022). "WAP-Cre and MMTV-Cre mice have been able to generate hereditary breast cancer models specifically by modeling the heterozygous mutations observed in the BRCA1/BRCA2 genes." (PMID 35186735, 2022). "In individuals harboring mutations in BRCA1/2 genes, the probability of developing breast cancer over a lifetime is around 85%, and that of EOC is about 20–40%." (PMID 36010882, 2022). "The estimated average cumulative risk of breast cancer to age 70 years was estimated to be 52% (95% CI, 26–69%) for BRCA1 mutation carriers and 47% (95% CI, 29–60%) for BRCA2 mutation carriers." (PMID 35409110, 2022). "In line with this understanding, we previously reported an increased risk of breast cancer with oral contraceptive use at an early age in BRCA1 mutation carriers." (PMID 35668475, 2022). "We observed that in BRCA1 mutation carriers the median time from primary breast cancer diagnosis until a DNA test, was much shorter in the chemotherapy group (1.0 year) than in the non-chemotherapy group (3.4 years)." (PMID 34929424, 2022). "A further retrospective cohort study (725 BRCA1/2 mutation carriers) reported a 42% risk reduction for developing breast cancer among participants with increasing levels of sports activity prior to, but not after, age 3011." (PMID 35190584, 2022). "Thirteen percent of participants reported that they were confused about the concept of the BRCA1/2 genes and 7.8% about the increased risk of breast cancer when carrying a BRCA mutation." (PMID 36387260, 2022). "Saliva collected from patients with breast cancer with BRCA1 mutation is characterized by an enhanced antioxidant capacity and oxidative damage to proteins and lipids." (PMID 35629940, 2022). "Unique mutational signatures and similar phenotypes found among BRCA1-mutated breast cancer make it an ideal candidate for discovering shared neoantigens within the group." (PMID 36298462, 2022). "Frequencies of BRCA pathogenic variant (PV) carriers among ER+/HER2- breast cancer patients have been underestimated, and many experts assume than 50% of all BRCA1/2 mutated breast cancers are of ER+/HER2- subtype." (PMID 35158866, 2022). "Quantifying breast cancer risk associated with a mosaic BRCA1 variant was complicated by the impossibility of predicting the proportion of breast tissue with the (likely/) pathogenic variant." (PMID 36068545, 2022). "Breast cancers with germline BRCA1 or BRCA2 pathogenic or likely pathogenic variants and biallelic inactivation show evidence of deficiency in homologous recombination repair." (PMID 36085046, 2022). "BRCA1 L1780P BRCT domain mutation has been recognized as a pathogenic mutation in patients with breast cancer." (PMID 35626017, 2022). "Sanger sequencing or a 98-gene panel sequencing assay was used to screen for BRCA1 germline small mutations in 1151 breast cancer patients with high-risk factors." (PMID 34403063, 2022). "Significantly, PTEN loss is highly associated with BRCA1-defective breast cancers, probably due to genomic instability resulting from deficient DSB repair, and the resulting PI3K/AKT activation stimulates the growth of those cancers." (PMID 35681784, 2022). "Approximately 5-10% of breast cancer can be attributed to inherited genetic mutations in high penetrance genes such as BRCA1/2." (PMID 36387260, 2022).
breast cancer (continued). "Randomized controlled trials are needed to evaluate the clinical effectiveness of denosumab for BRCA1-associated breast cancer prevention in these high-risk women." (PMID 35418083, 2022). "To validate the role of EZH2 as a therapeutic target and to identify new synergistic drug combinations, we performed a high-throughput drug combination screen in various cell lines derived from BRCA1-deficient and -proficient mouse mammary tumors." (PMID 35715861, 2022). "Talazoparib, a poly(ADP-ribose) polymerase enzyme inhibitor, is approved for the treatment of patients with germline BRCA1/2 (gBRCA1/2)-mutated HER2-negative advanced breast cancer." (PMID 35907135, 2022). "Women who inherit a pathogenic germline mutation in the BRCA1 gene face a very high lifetime risk of developing breast cancer, estimated at 72% by age 80 compared to 11% among women in the general population." (PMID 35418083, 2022). "In this way, the study showed that, in fact, the risk of breast cancer is lower in the central regions of the BRCA1/2 genes." (PMID 35805026, 2022). "In our research, we demonstrated that BRCA1 germline mutation breast cancer patients with high CIN values suffered from shorter DFS." (PMID 34403063, 2022). "For HBOC, there is some observational evidence to suggest that exposure to diagnostic radiation, including mammography, at a young age is associated with increased risk for breast cancer among females with disease-causing BRCA1/2 variants." (PMID 36353115, 2022). "CDK5RAP3 expression is linked to breast cancer survival and its genetic variations are associated with BRCA1/2 mutation carriers." (PMID 35053516, 2022). "Women with BRCA1/2 gene mutations have a cumulative risk of about 70% up to the age of 80 for breast cancer and about 44% (BRCA1) and 17% (BRCA2) for ovarian cancer." (PMID 35139834, 2022). "BRCA1/2 mutations are estimated to be present in 25% of patients with ovarian cancer and 3% of patients with breast cancer." (PMID 36350633, 2022). "In a study, this mutation was found to protect against the development of breast cancer in BRCA1/2 mutation mutants." (PMID 36010882, 2022). "Historically, PARP inhibition induced apoptosis through synthetic lethality when combined with BRCA1/2 mutations in breast cancer patients resulting from unrepaired strand breaks." (PMID 35747808, 2022). "BRCA1/2 alterations increase females’ lifetime breast cancer risk to 40 – 90%, ovarian cancer to 10 – 60%, and males’ lifetime prostate cancer risk to ~ 10 – 25%." (PMID 35933387, 2022). "Other examples include the Maturity-onset diabetes of the young (MODY) forms of diabetes or breast cancer due to deleterious variants in the BRCA1 and BRCA2 genes." (PMID 36013215, 2022). "Breast cancer susceptibility genes 1 or 2 mutations (BRCA1/2) are linked with hereditary breast and ovarian cancers (HBOC), 5%–10% of breast cancers and 10%–15% of ovarian cancers possess a BRCA1/2 mutation." (PMID 36531159, 2022). "Loss of 53BP1 restored DNA end resection and rescued the HR defects, thereby rendering BRCA1-deficient mouse mammary tumors resistant to PARPi." (PMID 36284291, 2022).
breast cancer (continued). "Breast cancers from both BRCA1 and BRCA2 germline mutation carriers have been previously shown to be sensitive to platinum-based chemotherapeutic regimens." (PMID 35857626, 2022). "Dysbindin domain-containing protein 2 variant DBNDD2:34 that was upregulated in BRCA1 mutated breast cancer was found downregulated in the AKT1 silenced sample compared to control (siNoN)." (PMID 35892586, 2022). "Mutations in the gene has been associated with breast cancer development with reports suggesting that about 72% of women inheriting a mutated BRCA1 gene develop breast cancer by the age of 80 years." (PMID 36942145, 2022). "In the OlympiA trial, the efficacy of iPARP–olaparib therapy was proven in BRCA1/2 gene mutation carriers with diagnosed breast cancer at high risk of recurrence." (PMID 35887761, 2022). "The cumulative male breast cancer risk is estimated at 0.1–1.5% in BRCA1 P/LPV carriers and at 1.9–7.7% in BRCA2 P/LPV carriers." (PMID 36230512, 2022). "Given the lower population prevalence of BRCA1 PVs, the risk of breast cancer in some women with a BRCA1 PV will be sufficient to recommend MRI screening in BRCA1 PV carriers<30 years." (PMID 33758026, 2022). "At least eight genes were found to be significantly associated with breast cancer risk: BRCA1 (MIM#113705), BRCA2 (MIM#600185), ATM (MIM#607585), BARD1 (MIM #601593), CHEK2 (MIM#604373), PALB2 (MIM#610355), RAD51C (MIM#602774), and RAD51D (MIM#602954)." (PMID 36139699, 2022). "At present, the best individualised breast cancer risk assessments in constitutional BRCA1/BRCA2 carriers are estimated using a validated programme such as CanRisk." (PMID 36068545, 2022). "BRCA1/2 pathogenic variants are also enriched in bilateral breast cancer and patients with family history of breast or other cancers." (PMID 36439508, 2022). "About 5–10% of all breast cancer cases can be attributed to hereditary factors and up to 30% of which are due to germline mutations in BRCA1/2 genes." (PMID 35333900, 2022). "Patients with BRCA1/2 mutations have a 72% and 69% lifetime risk of developing breast cancer respectively, with increased ovarian cancer risks." (PMID 35813042, 2022). "It is known that proportion of BRCA1/2 mutation career is 2.3% in patients with HER2-positive breast cancer." (PMID 35191009, 2022). "The patients with BRCA1 mutation had the worst survival in both breast cancer and ovarian cancer, compared to the patients with BRCA2 mutation and patients with no mutations." (PMID 35205313, 2022). "We retrospectively reviewed the medical records of women with a personal history of unilateral breast cancer carrying pathogenic variants in BRCA1/2 who were diagnosed between 1996 and 2012." (PMID 36685664, 2022). "The breast cancer susceptibility genes BRCA1 and BRCA2 (BRCA genes) are well-known tumor suppressors whose inactivation increases the probability of developing cancer, particularly of breast and ovarian origin, but also in the pancreas and prostate." (PMID 36969741, 2022). "Our molecular analysis demonstrates that the expression signature of ATP11BloPTDSS2hi exposes PS on the outer leaflet of the cell membrane, which serves as a global immunosuppressive signal and synergizes with BRCA1 deficiency in breast cancer metastasis." (PMID 35025764, 2022). "Pathogenic variants in non-BRCA1/BRCA2 breast cancer susceptibility genes accounted for 1.8% of our cohort." (PMID 35039564, 2022). "The estimated lifetime risk of developing breast cancer is 40%–80% in patients carrying either BRCA1/2 mutation." (PMID 36531159, 2022).
breast cancer (continued). "The SBC signature was significantly enriched in samples with higher breast cancer risk (i.e., nulliparous, and BRCA1/2mut carriers) compared to those of lower risk (FDR < 0.05 for all cases)." (PMID 36476730, 2022). "In men, BRCA2 mutations and, less frequently, BRCA1 mutations are established risk factors of breast cancer." (PMID 35656339, 2022). "We were also able to observe induction of SNAI2 in BRCA1-mutated ovarian and breast cancer cell lines COV362 and MDAMB436." (PMID 35864202, 2022). "Approximately 10% of men with breast cancer are genetically predisposed, which, in most cases, is determined by hereditary BRCA1 and BRCA2 mutations." (PMID 35303741, 2022). "The odds ratio for the association between the PRSER+ and ER-positive breast cancer risk for BRCA1 carriers (OR = 1.79, 95% CI = 1.30 to 2.48) was somewhat higher compared with the odds ratio for overall breast cancer." (PMID 34320204, 2022). "Seven deletion and two duplication regions were associated with breast cancer risk at p < 0.001; of these, deletions within the BRCA1 region achieved p < 10−6." (PMID 35042965, 2022). "Serving as a positive control, the gene expression of BRCA1, whose promoter methylation is associated with breast cancer induction, was measured and was found to be increased after decitabine treatment." (PMID 35115484, 2022). "A 2015 population-based study of 396 African American women diagnosed with breast cancer before age 50 found that 12% of the study participants had BRCA1/2 mutations, more than double what was found in white women." (PMID 35742117, 2022). "BRCA1 participates in the regulation of various genes’ expressions, which is associated with an increased risk of breast cancer." (PMID 35163783, 2022). "His mother suffered from breast cancer, and because of the genetic risk, he was evaluated for breast cancer gene 1 (BRCA1)/breast cancer gene 2 (BRCA2) mutation and was positive." (PMID 37435457, 2022). "We applied in silico and in vitro analyses to characterise a novel risk association between deletions overlapping SULT1A1 (OMIM 171150) and decreased breast cancer risk for BRCA1 pathogenic variant carriers." (PMID 36203093, 2022). "the study reports for the very first time in Ghana, BRCA1 gene variants and finger dermatoglyphics among breast cancer patients." (PMID 36942145, 2022). "The hyaluronan-mediated motility receptor (HMMR, also known as RHAMM) interacts with BRCA1 to regulate cell division and apicobasal polarization of mammary epithelial cells, and is a potential modifier of BRCA1-associated breast cancer risk." (PMID 35393420, 2022). "CAPTORs can also be customised for clinical diagnoses, correcting systematic sequencing errors and improving the diagnosis of pathogenic BRCA1/2 variants in breast cancer." (PMID 36307482, 2022). "PARP inhibitors, including talazoparib and olaparib, are currently approved for the treatment of HER2-negative advanced breast cancer in patients who harbor a genomic BRCA1 and/or BRCA2 (gBRCA1/2) mutation." (PMID 36253484, 2022). "One of the risk factors for breast and ovarian cancers is mutations of breast cancer susceptibility genes, which were known to be BRCA1 and BRCA2—the dynamic regulators of genomic integrity." (PMID 35205313, 2022).
breast cancer (continued). "Both BRCA1-deficient and -reconstituted human breast cancer cell lines significantly increased M2-like polarization of THP1 macrophages in co-culture experiments." (PMID 35641483, 2022). "With the trend towards larger gene panels for breast cancer predisposition testing, increasing numbers of patients will be tested for BRCA1/BRCA2 and moderate risk breast CSGs." (PMID 34983940, 2022). "Treatment of BRCA1/2 mutational breast cancer with PARP inhibitor is a paradigm of “Synthetic lethality” therapy." (PMID 36461092, 2022). "Based on the BRCA1-associated breast cancer risk, annual breast MRI surveillance was offered and organised for both patients." (PMID 36068545, 2022). "It has been reported that breast cancer susceptibility gene 1 (BRCA1), as a breast cancer suppressor gene, play a crucial role in keeping DNA intact and maintaining genomic stability." (PMID 36192752, 2022). "Our results suggest that loss of BRCA1 also contributes to the potential of breast cancer cells to promote pro-tumor M2-like macrophage polarization." (PMID 35641483, 2022). "Data from studies conducted among women with a BRCA1 mutation further support this pathway in BRCA1-associated breast cancer development." (PMID 35418083, 2022). "As described in the introduction, loss of BRCA1 protein staining in the nucleus was often observed in sporadic breast cancers, and this phenomenon was associated with high-grade and poor survival." (PMID 34996912, 2022). "Compared to BRCA1/2 mutation carriers, which account for up to 22–30% of the hereditary breast cancer cases, less is known about the other 70% of genetic breast cancer patients." (PMID 35681739, 2022). "Predicted genetic risk for breast cancer varied by 15-fold across the embryos, with OR ranging from 0.35 (non-BRCA1 carrier with low PRS) to 5.35 (BRCA1 carrier with high PRS)." (PMID 35314819, 2022). "The use of germline genetic testing for breast cancer susceptibility has also concomitantly increased over the same time beginning with the discovery of the BRCA1 gene (in 1994) and the BRCA2 gene (in 1995)." (PMID 36685664, 2022). "Nevertheless, less posterior attenuating was observed in documented BRCA1 mutation and familial breast cancers." (PMID 36199374, 2022). "In clinical trials, PARP inhibitors are mainly concentrated in cancer patients with homologous recombination repair defects, including breast cancer and ovarian cancer patients with BRCA1 and BRCA2 mutations (gBRCA1/2m)." (PMID 35963853, 2022). "This study evaluates overall survival (OS) following CPM among women carrying germline pathogenic variants in BRCA1/2 with a personal history of unilateral breast cancer in a contemporary cohort." (PMID 36685664, 2022). "Molecular subtypes of breast cancer and variant location of BRCA1 gene: out of the seventy samples from breast cancer participants, 21 amplified DNA samples from breast cancer participants were selected through simple random sampling and sequenced." (PMID 36942145, 2022). "Of the breast cancer susceptibility genes which have been identified nowadays, BRCA1 and BRCA2 are the most fundamental “high-risk” genes with several cases of breast and ovarian cancer accounting for most of the families." (PMID 35837379, 2022). "Several studies have also indicated BRCA1 epigenetic inactivation caused poor survival was related with increased DNMT3B in sporadic breast cancers." (PMID 35620052, 2022). "We plan to proceed to in vivo studies with the validated neoantigen candidates by using those shared neoantigens to immunize mouse models with BRCA1-mutated breast cancer." (PMID 36298462, 2022). "In breast cancer patients with germline pathogenic BRCA1/2 mutations, cancer cells harbor homologous recombination repair deficiency (HRD) due to malfunction of BRCA1 or BRCA2 protein in DNA damage repair." (PMID 35855837, 2022).